SNF8 (SNF8 subunit of ESCRT-II)
Description:
Component of the endosomal sorting complex required for transport II (ESCRT-II), which is required for multivesicular body (MVB) formation and sorting of endosomal cargo proteins into MVBs, and plays a role in autophagy. The MVB pathway mediates delivery of transmembrane proteins into the lumen of the lysosome for degradation. The ESCRT-II complex is probably involved in the recruitment of the ESCRT-III complex. The ESCRT-II complex may also play a role in transcription regulation by participating in derepression of transcription by RNA polymerase II, possibly via its interaction with ELL. Required for degradation of both endocytosed EGF and EGFR, but not for the EGFR ligand-mediated internalization. It is also required for the degradation of CXCR4. Required for the exosomal release of SDCBP, CD63 and syndecan.
Synonyms: EAP30; VPS22; Dot3; DEE115; NEDOA
Tractability: Antibody: its Gene Ontology location is reachable by antibodies, with high confidence; UniProt places it where antibodies can reach, with medium confidence. PROTAC: ubiquitination databases record sites on it; its protein half-life has been measured.
Gene: Protein-coding gene on chromosome 17 (48,929,316 to 48,944,842, reverse strand). Ensembl gene ENSG00000159210.
Subcellular location: Cytoplasm; Endosome membrane; Nucleus; Late endosome membrane
Subcellular location (Human Protein Atlas): Cytosol; Nucleoplasm
Pathways (Reactome):
Disease: HCMV Late Events
Vesicle-mediated transport: Endosomal Sorting Complex Required For Transport (ESCRT)
Gene Ontology:
Molecular function: channel regulator activity; lipid binding; protein binding; protein homodimerization activity
Biological process: early endosome to late endosome transport; endocytic recycling; macroautophagy; multivesicular body assembly; multivesicular body sorting pathway; positive regulation of exosomal secretion; positive regulation of gene expression; positive regulation of protein catabolic process; regulation of MAP kinase activity; regulation of protein catabolic process; regulation of protein complex stability; regulation of transcription by RNA polymerase II; membrane fission; protein transport to vacuole involved in ubiquitin-dependent protein catabolic process via the multivesicular body sorting pathway
Cellular component: cytoplasm; cytosol; endosome membrane; ESCRT II complex; extracellular exosome; late endosome membrane; membrane; nucleoplasm; nucleus; perinuclear region of cytoplasm; plasma membrane; recycling endosome; transcription regulator complex
Genetic constraint (gnomAD): Loss-of-function variants: 18 observed, 31.29 expected, observed/expected ratio (o/e) 0.58, 90% interval 0.4 to 0.85. The upper end of that interval is the gene's LOEUF score, 0.85, which puts it in group 3 of 6, group 1 being the genes least tolerant of losing a copy. Missense variants: 250 observed, 318.15 expected, observed/expected ratio (o/e) 0.79, 90% interval 0.71 to 0.87. Synonymous variants: 121 observed, 125.47 expected, observed/expected ratio (o/e) 0.96, 90% interval 0.83 to 1.12.
Homologues: Orthologues: chimpanzee SNF8 (100% identical), macaque SNF8 (100% identical), pig SNF8 (99% identical), mouse Snf8 (98% identical), rat Snf8 (98% identical), guinea pig SNF8 (97% identical), rabbit SNF8 (91% identical), dog SNF8 (87% identical), tropical clawed frog snf8 (86% identical), zebrafish snf8 (85% identical), Drosophila melanogaster lsn (49% identical), Caenorhabditis elegans vps-22 (49% identical).
Diseases named in the same sentence as SNF8 in open-access papers:
SNF8 is named in the same sentence as 22 diseases in open-access papers, as found by Europe PMC text mining. Sharing a sentence is not in itself a finding about the gene and the disease. The quoted sentences say what the papers report.
and epileptic encephalopathy (1 paper, 2024). "We identified bi-allelic variants in SNF8, encoding a subunit of the ESCRT-II complex, in individuals presenting with a disease spectrum ranging from epileptic encephalopathy to syndromic optic atrophy—findings also present in a zebrafish model." (PMID 38423010, 2024).
breast carcinoma (1 paper, 2012). "One of the most intriguing fusion partners is RPS6KB1, which we found fused to SNF8 and TMEM49 (RPS6KB1-SNF8, RPS6KB1-TMEM49), and that has been found in a subset of clinical breast cancer samples harboring 17q23-chromosome amplification, albeit with structural heterogeneity." (PMID 23119097, 2012).
coronary artery disease (1 paper, 2021). "Partial QTLs or SNPs have been associated with coronary artery disease (SNF8 and UBE2Z)." (PMID 35052342, 2021).
insomnia (1 paper, 2025). A sleep disorder characterized by difficulty in falling asleep and/or remaining asleep. "Genome-wide association studies identified a genetic locus (near ATP5G1, UBE2Z, SNF8, IGF2BP1 and GIP) linked to insomnia and CVD." (PMID 40176577, 2025). "This study is the first to identify four genes at a single locus that link CVD and insomnia: ATPsynC, Bruce, lsn and Imp (ATP5G1, UBE2Z, SNF8 and IGF2BP1 in humans)." (PMID 40176577, 2025).
myocardial infarction (1 paper, 2018). Gross necrosis of the myocardium, as a result of interruption of the blood supply to the area, as in coronary thrombosis. "The last cluster of three shared SNPs map to the SNF8-GIP region (17q21.32); although the shared SNPs have not been reported in GWAS, other SNPs in this region are associated with CAD and myocardial infarction." (PMID 29309429, 2018).
Pachygyria (1 paper, 2024). Pachygyria is a malformation of cortical development with abnormally wide gyri with sulci 1,5-3 cm apart and abnormally thick cortex measuring more than 5 mm (radiological definition). "Identification of more individuals with SNF8-associated disease and further studies in gyrencephalic animals will help to clarify whether pachygyria is indeed associated with a loss of SNF8 or rather an unrelated feature." (PMID 38423010, 2024).
tumor (3 papers, 2020 to 2024). "Together with previous data, we proposed a novel circRNA exosome secretion mechanism: circRHOBTB3 is specifically sorted into exosomes via the interaction between the ESCRT-II complex member SNF8 and its own specific element and is secreted outside of tumor cells." (PMID 35148775, 2022).
neurodegenerative disease (2 papers, 2022 to 2024). A disorder of the central nervous system characterized by gradual and progressive loss of neural tissue and neurologic function. "We provide evidence for an association of bi-allelic SNF8 variants with a neurodevelopmental/neurodegenerative disease entity with a variable phenotype due to defective ESCRT-II function, at least in part ascribed to an altered autophagic flux." (PMID 38423010, 2024).
cancer (1 paper, 2021). A tumor composed of atypical neoplastic, often pleomorphic cells that invade other tissues. "SNF8, UBE2Z, CALCOCO2, and ATP5MC1 have been shown a core function in metabolic disease and cancer." (PMID 35052342, 2021).
SNF8 also shares sentences with these, for which no sentence is quoted: infection (2 papers); viral infections (2); Alzheimer disease (1); autoimmune disease (1); diabetes (1); hematological malignancies (1); hepatoma (1); infectious disease (1); Insulin resistance (1); malignant melanoma (1); metabolic disease (1); migraine (1); optic atrophy (1).